DDAH2 (DDAH family member 2, ADMA-independent)
Diseases named in the same sentence as DDAH2 in open-access papers (continued):
Sharing a sentence is not in itself a finding about the gene and the disease.
psychiatric disorder (2 papers, 2022 to 2025). A disorder characterized by behavioral and/or psychological abnormalities, often accompanied by physical symptoms. "A recent functional genomics study identified DDAH2 as a key gene with pleiotropic effects across psychiatric disorders linked to an allele-specific methylation SNP." (PMID 41017816, 2025). "This study’s objective was to estimate DDAH1 and DDAH2 associations with biological processes implicated in major psychiatric disorders using publicly accessible expression databases." (PMID 36233204, 2022). "We found that correlations between expression levels of DDAH1 or DDAH2 and genes associated with mental illness are lost in cortical samples from psychiatric patients." (PMID 36233204, 2022). "This disarrangement appears in the loss of expression level correlations between DDAH1 or DDAH2 and genes associated with psychiatric disorders and reduced functional similarity of DDAH1 or DDAH2 co-expressed genes in the patient groups." (PMID 36233204, 2022). "Our results suggest a possible involvement of DDAH1 and DDAH2 in the pathophysiology of psychiatric disorders." (PMID 36233204, 2022). "Considering that the gene’s co-expression mirrors the similar biologic function of these genes, we attempted to compare DDAH1 and DDAH2 co-expression patterns in control subjects and patients with psychiatric disorders." (PMID 36233204, 2022).
metabolic disease (1 paper, 2025). A congenital disorder (due to inherited enzyme abnormality) or acquired (due to failure of a metabolically important organ) disorder resulting from an abnormal metabolic process. "In the lncRNA-miRNA-mRNA network, NEAT1 regulates CAPG/DDAH2 through miR-1179/miR-1276, which is consistent with previously reported pivotal roles of NEAT1 in inflammation and metabolic diseases." (PMID 41050938, 2025).
DDAH2 also shares sentences with these, for which no sentence is quoted: cardiovascular disease (3 papers); Alzheimer disease (2); Hyperglycemia (2); lung carcinoma (2); acute myocardial infarction (1); autism spectrum disorder (1); benign prostate hypertrophy (1); cardiac hypertrophy (1); choroidal neovascularization (1); colorectal adenocarcinoma (1); diabetic neuropathy (1); esophageal tumors (1); gastric cancer (1); gestational diabetes mellitus (1); heart failure (1); hyperuricemia (1); inflammation (1); injury (1); insomnia (1); iron overload (1); kidney disease (1); lung squamous cell carcinoma (1); major depressive disorder (1); multiple sclerosis (1); oral squamous cell carcinoma (1); pancreatic adenocarcinoma (1); preeclampsia (1); pulmonary fibrosis (1); retinopathy (1); senile cataract (1).
A further 5 diseases each share a sentence with DDAH2 in 1 paper.